TIAM1 (TIAM Rac1 associated GEF 1)
Diseases named in the same sentence as TIAM1 in open-access papers (continued):
Sharing a sentence is not in itself a finding about the gene and the disease.
lymphoma (16 papers, 2008 to 2023). A malignant (clonal) proliferation of B- lymphocytes or T- lymphocytes which involves the lymph nodes, bone marrow and/or extranodal sites. "TIAM1 was initially found in mouse T lymphoma cells and then confirmed as a key gene associated with cancer malignancy 30-35." (PMID 35844783, 2022). "TIAM1 (T-lymphoma invasion and metastasis) is a Rac-specific guanine nucleotide exchange factor and has been shown to control tight junction biogenesis in KC, thereby controlling barrier formation." (PMID 37675143, 2023). "This included transcript levels of two guanine nucleotide exchange factors (GEFs), TRIO and TIAM1, which we subsequently validated as being up-regulated in Eμ-Myc/RelAT505A lymphomas using qPCR." (PMID 36240067, 2022). "In multidrug-resistant lymphoma cell lines expressing a higher levels of Tiam1, the researchers found that dual inhibition of Tiam1-Rac1 and Notch pathways would be an important treatment for overcoming the resistance of lymphoma cells to adriamycin." (PMID 34079763, 2021). "In 1994, Habets and his coworkers first identified Tiam1 and found that Tiam1 confers an invasive phenotype to murine T-lymphoma cells." (PMID 33604328, 2020). "TIAM1 (T cell lymphoma invasion and metastasis 1) is initially found in mice T lymphoma cells and considered as a metastasis-related gene." (PMID 32948241, 2020). "It has previously been reported that Tiam1 is highly expressed in lymphoma, leukemia, and many solid tumors including pancreatic, breast, bladder, lung, colorectal, gastric, liver, ovarian, prostate, and neck squamous cell cancer." (PMID 29416753, 2018). "Despite many studies on the role of Tiam1 in various types of tumors, surprisingly little information is available about the role of Tiam1 in lymphoma." (PMID 29416753, 2018). "Tiam1, a potential biomarker of tumor progression, metastasis, and chemoresistance, was activated in our 3D lymphoma model." (PMID 29416753, 2018). "To explore the relevance of a 3D lymphoma cell culture in AmCA hydrogels to tumor growth in vivo, we compared excised tumor tissue with the 2D- and 3D-lymphoma cell cultures in terms of Tiam1, Rac1, and c-Myc expression." (PMID 29416753, 2018). "The augmented sensitivity to doxorubicin by combined pretreatment with Tiam1 and Notch inhibitors was more prominent in 3D lymphoma spheroids compared to the 2D-cultured cells in both cell types." (PMID 29416753, 2018). "This second messenger is known to bind a Rac1 specific GEF, Tiam1 (T lymphoma invasion and metastasis)." (PMID 26872368, 2016). "Another gene, TIAM1 (T-cell lymphoma invasion and metastases), is not only involved in lymphoma but in many cancers where Tiam1 is proposed as a prognostic marker for breast, colon and hepatocellular cancer progression and metastasis." (PMID 26959888, 2016). "For example, the recruitment of Tiam1 (T lymphoma invasion and metastasis), a GEF for Rac1, is important for epithelial polarization as it promotes perijunctional actin polymerization and tight junctions formation." (PMID 26872368, 2016). "It has been reported that Tiam1 participates in cytoskeleton rearrangement, and cell migration and mobility in T-lymphoma cells, fibroblasts and epithelial cells." (PMID 24661909, 2014). "Tiam1, also called T-cell lymphoma invasion and metastasis-inducing factor, was first identified as a metastasis-related gene in the aggressive mice T lymphoma cells." (PMID 24661909, 2014). "Three such GEFs which regulate the Rho family of GTPases are Trio, Vav1 and TIAM-1 (T-lymphoma invasion and metastasis gene)." (PMID 18925966, 2008). "In addition, TIAM1-overexpressed multidrug-resistant lymphoma cell lines targeted with dual TIAM1-RAC1 and NOTCH pathway inhibitors improved sensitivity to adriamycin." (PMID 34830751, 2021). "Moreover, Tiam1 and Rac1 were overexpressed in a 3-D model of lymphoma, where treatment with Tiam1/Rac1 inhibitor NSC23766 overcame chemoresistance to doxorubicin." (PMID 32322580, 2020).
lymphoma (continued). "In diabetes, GEF, T cell lymphoma invasion and metastasis (Tiam1), is shown to be critical in orchestrating Rac1 activation; activation of Tiam1-Rac1-Nox2 signaling axis, an early event in the pathogenesis of diabetes, leads to mitochondrial damage and accelerated capillary cell apoptosis." (PMID 31277234, 2019). "Furthermore, it was shown that multidrug-resistant lymphoma cell lines express a higher Tiam1 level compared to multidrug-sensitive lymphoma cell lines." (PMID 29416753, 2018). "Importantly, Tiam1 as a potential biomarker of tumor initiation and progression, metastasis, and chemoresistance in many tumor cells was activated in our 3D lymphoma model." (PMID 29416753, 2018). "Tiam1 was originally identified a metastasis-related gene of T lymphoma." (PMID 24661909, 2014). "Studies have shown that over expression of TIAM-1 protein confers an invasive phenotype in T-lymphoma cells suggesting that increased TIAM-1 levels may lead to tumour progression and invasion." (PMID 18925966, 2008). "Despite the fact that in PTCLs we still lack of information about its upstream regulators, Tiam-1 has been found overexpressed during lymphoma invasion and metastasis where promotes infiltration of T lymphoma cells into fibroblast monolayers." (PMID 33928032, 2021). "Notably, we confirmed in the present study that Tiam1 is involved in chemoresistance against doxorubicin in EL4 T and A20 B lymphoma cells." (PMID 29416753, 2018). "Importantly, we report that the combined inhibition of dual oncotargets, Tiam1 and Notch, could be a new therapeutic approach to overcome the resistance of EL4 T and A20 B lymphoma cells against doxorubicin." (PMID 29416753, 2018).
gastric cancer (14 papers, 2010 to 2025). A primary or metastatic malignant neoplasm involving the stomach. "TIAM Rac1 Associated GEF 1 (TIAM1) is overexpressed in various cancers, such as breast, lung, and gastric cancers." (PMID 37438760, 2023). "Studies also showed that up-regulation of Tiam1 was associated with metastasis of hepatocellular carcinoma and gastric cancer." (PMID 24661909, 2014). "In gastric cancer, miR-10b-5p targets oncogenic proteins such as TIAM1 and MAPRE1, and its overexpression inhibits proliferation, migration, and invasion while inducing apoptosis, effectively modulating the TME to suppress tumor progression." (PMID 39796267, 2025). "In gastric cancer, miR-10b-5p functions as a TSmiR by targeting oncogenic proteins such as TIAM1 and MAPRE1." (PMID 39796267, 2025). "The CBFβ/RUNX3-miR-10b-5p-TIAM1 molecular axis further inhibits gastric cancer cell proliferation, migration, and invasion." (PMID 39796267, 2025). "Adding miR-10b-5p to gastric cancer cells and implanting them subcutaneously in mice inhibits the proliferation and migration of gastric cancer cells due to the upregulation of Tiam1." (PMID 35741311, 2022). "For example, miR-10 regulates the oncogene USF2 in myeloid leukaemia, BDNF in cervical cancer, and Tiam1 in gastric cancer." (PMID 35573695, 2022). "Since today, different groups have confirmed a role for Tiam1 in cell migration and actin cytoskeleton modification in different cancer- and normal cells, such as in gastric cancer or Schwann cells." (PMID 30558116, 2018). "Identified miR-29c targets include CDK6 in RCC2 in gastric carcinoma, TIAM1 in nasopharyngeal carcinomac and mantle cell lymphoma." (PMID 29262657, 2017). "Additionally, miR-10b-5p suppresses tumor growth in gastric cancer xenograft models by downregulating TIAM1." (PMID 39796267, 2025). "Its downregulation in gastric cancer tissues leads to increased expression of TIAM1 and MAPRE1." (PMID 39796267, 2025). "As a tumor suppressor, miR-10b-5p targets the oncogenic proteins TIAM1 and MAPRE1 in gastric cancer cells." (PMID 39796267, 2025). "Overexpression of GEFs, such as Tiam1 in gastric, prostate cancer, lung adenocarcinoma, and in squamous-cell carcinoma of the head and neck (SCCHN), and Vav3 in prostate and gastric cancer may enhance Rac activity." (PMID 30558116, 2018).
hepatocellular carcinoma (14 papers, 2014 to 2023). A malignant tumor that arises from hepatocytes. "We have demonstrated that T lymphoma invasion and metastasis 1 (Tiam1) gene is associated with the poor prognosis of patients with hepatocellular carcinoma (HCC), and we used a computational approach to identify miR-141 as a Tiam1-targeting microRNA (miRNA)." (PMID 24551096, 2014). "Recent study indicated that miR-377 targeted oncogenic ETS1 gene and functioned as a tumor suppressor in CCRCC, and miR-377 inhibited TIAM1 expression and repressed cell growth and metastasis in hepatocellular carcinoma." (PMID 27351135, 2016). "Our previous study showed that TIAM2 was overexpressed in a great majority (86%) of hepatocellular carcinoma (HCC) samples and significantly associated with TIAM1 overexpression." (PMID 26763486, 2016). "Moreover, the increased expression of Tiam1 has been reported in a variety of tumor types, such as colorectal carcinoma, hepatocellular carcinoma, prostate carcinoma, lung carcinoma and squamous-cell carcinoma of the head and neck." (PMID 27562113, 2016). "Overexpression of Tiam1 correlates with poor prognosis in hepatocellular carcinoma." (PMID 24661909, 2014). "miR-141 has been indicated to suppress the migration and invasion of hepatocellular carcinoma cells (HCC) by targeting Tiam1." (PMID 24992595, 2014). "Rab23 promotes hepatocellular carcinoma cell migration via the Rac1/TGF-β signaling pathway and promotes squamous cell carcinoma cell migration and invasion by regulating the integrin β1/Tiam1/Rac1 pathway." (PMID 32605180, 2020). "Previous studies have confirmed that T-lymphom invasion and metastasis gene (Tiam1) is a protein associated with the metastasis of hepatocellular carcinoma (HCC); however, we have not yet been successful in elucidating the specific mechanism of HCC." (PMID 29739365, 2018). "Moreover, SETDB1 is also considered an oncogene in hepatocellular carcinoma (HCC) cells because it boosts their proliferation and migration via interaction with T-cell lymphoma invasion and metastasis-inducing protein 1 (Tiam1)." (PMID 36582533, 2022).
thyroid cancer (13 papers, 2019 to 2025). "In addition, high levels of TIAM1 have been reported to increase the risk of recurrence of thyroid cancer, and the knockdown of TIAM1 significantly inhibited the migration and invasion potential of PTC cells in vitro." (PMID 35022405, 2022). "Previous studies have indicated that TIAM1 serves as an oncogene that promotes thyroid cancer metastasis and EMT through the Wnt/β-catenin pathway." (PMID 40819127, 2025). "The results demonstrated a reduction in ALKBH5 expression and an elevation in T-cell lymphoma invasion and metastasis 1 (TIAM1) expression in thyroid cancer." (PMID 39917169, 2025). "ALKBH5 modulates TIAM1 expression via m6A modification, thereby promoting ferroptosis in thyroid cancer cells." (PMID 39917169, 2025). "TIAM1 was elevated in thyroid cancer, and its knockdown repressed thyroid cancer cell proliferation." (PMID 38711144, 2024). "Tiam1 is highly expressed in thyroid cancer, and deletion of Tiam1 can inhibit the proliferation and metastasis of thyroid cancer cells." (PMID 38017477, 2023). "ALKBH5 also suppresses the progression of thyroid cancer by reducing the m6A level of TIAM1 and inducing ferroptosis through m6A-TIAM1-Nrf2/HO-1 axis." (PMID 37714846, 2023). "Our findings showed that miR-483 upregulated Tiam1/Rac1 signaling in thyroid carcinomas, possibly by downregulating Pard3." (PMID 30171257, 2019). "In the current study, we showed that Tiam1/Rac1 signaling was regulated by Pard3 in thyroid carcinomas." (PMID 30171257, 2019). "In addition, ALKBH5 overexpression downregulates TIAM1 expression by eliminating the m6A modification of TIAM1 mRNA, suppresses thyroid cancer cell proliferation and promotes ferroptosis by regulating the Nrf2/HO-1 pathway." (PMID 40819127, 2025). "In addition, TIAM1 was elevated in thyroid cancer, and TIAM1 knockdown repressed thyroid cancer cell proliferation and promoted ferroptosis through regulating Nrf2/HO-1 axis." (PMID 38003292, 2023). "However, recent research has demonstrated that ALKBH5, an RNA demethylase homologous to AlkB, can impede the progression of thyroid cancer by inducing ferroptosis in thyroid cancer cells via the TIAM1-Nrf2/Heme Oxygenase 1 (HO-1) axis, as evidenced by both in vitro and in vivo studies." (PMID 39917169, 2025). "Thyroid carcinoma tissues contain Tiam1, which is a Rac1-specific GEF that is overexpressed in thyroid carcinomas." (PMID 30171257, 2019).
ovarian carcinoma (12 papers, 2013 to 2024). A malignant neoplasm originating from the surface ovarian epithelium. "For example, MSTRG.73, a highly expressed lncRNA, targets the TIAM1 gene, which has been implicated in the invasive behavior of ovarian cancer, and down-regulation of TIAM1 is associated with increased aggressiveness of ovarian cancer cells." (PMID 38383305, 2024). "Additionally, miR-1271-5p directly targets TIAM1, a gene associated with metastasis, leading to the deactivation of the Notch signaling pathway and the consequent inhibition of ovarian cancer progression." (PMID 38793064, 2024). "It was also shown that Tiam1 expression is strongly associated with grade and outcome in ovarian carcinoma, and it may serve as a useful molecular marker for prognosis and clinical management." (PMID 29416753, 2018). "It was also suggested that miR-1271-5p binds to TIAM1 to inactivate the Notch signaling pathway to inhibit the growth and invasion of ovarian cancer cells." (PMID 36927770, 2023). "This unique miR-1271-5p-TIAM1-Notch1 axis in ovarian cancer cells provides a novel mechanism of targeting multiple players alone or in combination." (PMID 38269089, 2023). "The results suggest that Tiam1 can serve as a molecular prognostic marker for patients with ovarian cancer." (PMID 32443784, 2020). "An abundance of studied Tiam1 was documented in a cohort of ovarian carcinoma (59.3%), while in groups of benign and borderline tumors, higher expression was only identified in 12.5% and 31.6%, respectively." (PMID 32443784, 2020). "It regulates target oncogene (Tiam1), and reduce the migration, invasion and viability of ovarian cancer cells." (PMID 29270229, 2017). "Importantly, miR-1271-5p level was observed to be downregulated in ovarian cancer which in turn increased TIAM1 expression, leading to increased clonogenicity and invasive ability of these ovarian cancer cells." (PMID 38269089, 2023).
lung carcinoma (11 papers, 2014 to 2024). "The TCGA cohort (TCGA-LUAD/LUSC dataset) shows much lower expression levels of the TIAM1 gene in lung cancer tissues than those in normal tissues." (PMID 38711144, 2024). "In an EGFR mutant lung cancer setting, TIAM1 was shown to be required for proliferation and tumor growth." (PMID 37748077, 2023). "It functions as a tumor-suppressive miRNA in lung cancer by targeting TIAM1 to inhibit cell proliferation and invasion." (PMID 31889959, 2019). "We show that in epithelial cells, including lung carcinoma cells, stimulated with HGF, TIAM1—a critical regulator of cadherin-associated adhesion— is rapidly targeted for proteasome-dependent degradation via HUWE1-mediated ubiquitylation." (PMID 25543140, 2015). "Significantly, we show that HUWE1 stimulates human lung cancer cell invasion through regulating TIAM1 stability." (PMID 25543140, 2015). "Once again, to understand if the same mechanism is operating in lung carcinoma cells, we performed invasion assays in H1299, H358, and H522 lung cancer cell lines overexpressing either WT or 4x595R TIAM1." (PMID 25543140, 2015). "Up to now, several lung carcinomas potential markers had reported, such as Tiam1, MAT3, DNA methylome." (PMID 24946687, 2014). "Besides the pro-angiogenic effects of Sema4D, T-lymphoma invasion and metastasis-inducing protein-1 (Tiam1), was found to be able to promote the angiogenesis in cervical and lung cancer." (PMID 37986114, 2023). "Here, we show that the RAC1-selective guanine nucleotide exchange factor T cell invasion and metastasis-inducing protein 1 (TIAM1) promotes cell migration and invasion in the most common subtype of lung cancer, non-small-cell lung cancer (NSCLC), through an unexpected nuclear function." (PMID 37748077, 2023). "Finally, we demonstrate that HUWE1 and TIAM1 protein levels are inversely correlated in human lung carcinomas." (PMID 25543140, 2015). "Thus, HUWE1 appears essential for the invasion of lung carcinoma cells and this is entirely dependent on ubiquitylation of TIAM1." (PMID 25543140, 2015). "Based on this evidence, we conclude that aberrant HUWE1-mediated ubiquitylation of TIAM1 could contribute to the enhanced invasiveness of lung carcinoma cells." (PMID 25543140, 2015). "Here, we show that in response to HGF, HUWE1 ubiquitylates TIAM1 on lysine 595, triggering its proteasomal degradation predominantly at cell-cell adhesions, thereby enabling disassembly of cell junctions and induction of cell migration and invasion, including in lung carcinoma cells." (PMID 25543140, 2015). "The bioinformatic analyses also showed abnormal levels of TIAM1 and USP28 genes in the lung cancer tissues in the present study." (PMID 38711144, 2024). "We also show that TIAM1 and HUWE1 protein levels are negatively correlated in early-stage lung cancer specimens, consistent with this regulatory mechanism operating in human tumors." (PMID 25543140, 2015). "demonstrate that the E3 ligase HUWE1 degrades the RAC activator TIAM1 following HGF stimulation, promoting cell junction disassembly, motility, and invasion in epithelial cells including lung cancer cells." (PMID 25543140, 2015). "Thus, we anticipate that Tiam1 may reshape lung cancer cells to make them easier to spread to the lymph nodes or enhance reciprocity between tumor and stroma, though the precise molecular mechanism of Tiam1’s action in lung adenocarcinoma remains to be clarified." (PMID 24661909, 2014). "In lung cancer, levels of Tiam1 inversely correlate with expression of the E3 ubiquitin ligase HUWE1, which degrades Tiam1 specifically from cell-cell adhesions, indicating that localized regulation of GEF abundance may play a role in cancer." (PMID 27104658, 2016).